GARIN1B (golgi associated RAB2 interactor 1B)
Description:
RAB2B effector protein required for accurate acrosome formation and normal male fertility. In complex with RAB2A/RAB2B, seems to suppress excessive vesicle trafficking during acrosome formation.
Synonyms: FAM137A; FAM71F1; NYD-SP18; GARI-L1; GARIL1
Tractability: No criterion of Open Targets' tractability assessment is met for any kind of drug.
Gene: Protein-coding gene on chromosome 7 (128,709,061 to 128,731,743, forward strand). Ensembl gene ENSG00000135248.
Subcellular location: Golgi apparatus
Subcellular location (Human Protein Atlas): Golgi apparatus; Nuclear bodies; Cytosol; Nucleoplasm
Gene Ontology:
Biological process: acrosome assembly; acrosome reaction
Cellular component: Golgi apparatus
Genetic constraint (gnomAD): Loss-of-function variants: 35 observed, 40.23 expected, observed/expected ratio (o/e) 0.87, 90% interval 0.66 to 1.15. The synonymous counts are far from expectation, so gnomAD's model fits this gene poorly and the ratio says little. Missense variants: 371 observed, 427.35 expected, observed/expected ratio (o/e) 0.87, 90% interval 0.8 to 0.95. Synonymous variants: 131 observed, 172.44 expected, observed/expected ratio (o/e) 0.76, 90% interval 0.66 to 0.88.
Homologues: Orthologues: chimpanzee GARIN1B (97% identical), macaque GARIN1B (93% identical), pig GARIN1B (84% identical), dog GARIN1B (84% identical), guinea pig GARIN1B (82% identical), rat Garin1b (76% identical), mouse Garin1b (76% identical), rabbit GARIN1B (69% identical). Paralogues in human: GARIN1A (45% identical), GARIN3 (22% identical), GARIN5B (21% identical), GARIN4 (20% identical), GARIN2 (17% identical), GARIN5A (14% identical), GARIN6 (14% identical).
Diseases named in the same sentence as GARIN1B in open-access papers:
GARIN1B is named in the same sentence as 5 diseases in open-access papers, as found by Europe PMC text mining. Sharing a sentence is not in itself a finding about the gene and the disease. The quoted sentences say what the papers report.
Globozoospermia (2 papers, 2021 to 2024). Any structural anomaly of the acrosome resulting in a round sperm head. "In our previous study, we identified two globozoospermia-related genes: Golgi Associated RAB2 Interactor 1A (Garin1a; Fam71f2) and Garin1b (Fam71f1)." (PMID 38935810, 2024).
infertile (2 papers, 2021 to 2024). "Garin1a and Garin1b are predominantly expressed in the testes and KO of Garin1a and Garin1b causes subfertility and infertility in males, respectively, due to abnormal acrosomal morphology." (PMID 38935810, 2024).
GARIN1B also shares sentences with these, for which no sentence is quoted: Hypertension (1 paper); Obesity (1); teratozoospermia (1).